TNF (tumor necrosis factor)
Diseases named in the same sentence as TNF in open-access papers (continued):
Sharing a sentence is not in itself a finding about the gene and the disease.
Hyperglycemia (809 papers, 2006 to 2026). An increased concentration of glucose in the blood. "Hyperglycemia causes the emergence of elevated levels of advanced glycation-end products (AGEs), such as tumor necrosis factor (TNF) and reactive oxygen species (ROS)." (PMID 39857766, 2025). "While high glucose alone did not significantly affect platelet adhesion, its combination with TNF-α led to a marked increase, suggesting that hyperglycemia amplifies the pro-thrombotic environment caused by endothelial inflammation." (PMID 41326478, 2025). "Changes in the levels of IFN-γ, IL-17, and TNF-α, which are associated with both hyperglycemia and lung dysbiosis, are key players in the inflammatory circuits that control the progression of TB (Mori, Morrison and Blumenthal, 2021)." (PMID 39981106, 2024). "Production of hyperglycemia-related ROS is directly linked to the diabetic neuropathy pathogenesis by triggering the production of IL-1β and TNF-α." (PMID 38716357, 2024). "Group A (Normal control) has the lowest value of serum level of TNF-α compared to both B and C groups, hyperglycemia cause up-regulation of TNF-α concentration in diabetic rats." (PMID 38227584, 2024). "Prolonged hyperglycemia also shows dysregulation of TNF-α due to associated metabolic abnormalities." (PMID 37991535, 2024). "In a recent in vitro study, it was shown that in diabetic patients, hyperglycemia causes the activation of inflammatory pathways (inflammasome activation and increased TNFα expression), increased TNFα expression, and a reduction in autophagic flux." (PMID 38399561, 2024). "TNF-α causes muscle catabolism that is also mediated by glucocorticoids, as well as by glucagon, inducing hyperglycemia and amino acid uptake by the liver." (PMID 37235434, 2023). "Hyperglycemia caused a decrease in interleukin 6 (Il-6) and an increase in tumor necrosis factor alpha (Tnf-α), Il-10, F4/80, tumor growth factor beta (Tgf-β), and insulin-like growth factor 1 (Igf-1)." (PMID 36722656, 2023). "Elevated TNF-α levels and hyperglycemia are implicated in endothelial dysfunction in patients with diabetes." (PMID 37367894, 2023). "Oxidative stress, inflammation, tumor necrosis factor-α, hyperglycemia, peroxides, and hyperphosphatemia cause vascular calcification." (PMID 36638132, 2023). "TNF-α, along with associated hyperglycemia, stimulates apoptosis of fibroblasts, keratinocytes, and endothelial cells and accounts for the catabolic state of non-healing ulcers." (PMID 35836916, 2022). "Müller cells are especially involved in DR-associated inflammatory processes, as hyperglycemia induces Müller cells to express a number of pro-inflammatory cytokines, including IL-1β and TNF-α, which together upregulate IL-8." (PMID 35709240, 2022). "In our patients, stress hyperglycemia was also found to be independently associated with higher levels of IL-10 and by its ratio to TNF-α." (PMID 36059840, 2022). "Persistent hyperglycemia is linked to a chronic proinflammatory state, which results in elevated tumor necrosis factor α (TNFα) levels by inflammatory mediators including NFκB in DM." (PMID 35742837, 2022). "Inflammation normally affects insulin and glucose metabolism via cytokines such as TNF-α and Interleukin 6, and predispose to hyperglycemia." (PMID 37092113, 2022). "Inflammation will be more severe in the presence of hyperglycemia because hyperglycemia causes an increase in proinflammatory cytokines like TNF-α." (PMID 35016229, 2022). "Hyperglycemia has been linked to a pro-inflammatory state leading to increased production of interleukin-6 (IL-6) and tumour necrosis factor α (TNF-α)." (PMID 36463286, 2022). "Tumor necrosis factor-alpha (TNFα), a potent inducer and product of NF-κB stimulation has been implicated in disrupting insulin’s action during periods of hyperglycemia." (PMID 35624791, 2022).
Hyperglycemia (continued). "There was strong evidence that hyperglycemia causes the accumulation of advanced glycation endproducts (AGEs) to promote the activation of tumor necrosis factor α and osteoclast differentiation factor and improve osteoclast activity." (PMID 35637472, 2022). "The expression of the same proinflammatory cytokines implicated in hyperglycemia (IL-6, TNF-α, and CRP) has been reported to be associated with oral infection and PD." (PMID 34068221, 2021). "Amino acids, mTOR, p70S6 kinase, hyperinsulinemia, JNK, stress, hyperlipidemia, inflammation, TNFα, obesity, mitochondrial dysfunction, hyperglycemia, and DAG cause IRS-1 Ser phosphorylation." (PMID 34068151, 2021). "During hyperglycemia, proinflammatory cytokines, including tumor necrosis factor-α (TNF-α) and interleukin-1β (IL-β), elevate and cause nerve cell damage." (PMID 34685668, 2021). "It stated that when TNF-α was amplified, the insulin effect was diminished causing intensification of hyperglycemia, and thereby augmented the impact of NF-κB proteins." (PMID 34922513, 2021). "We also reported that hyperglycemia and TNF-α activate NF-κB and cause proliferation of VSMCs and apoptosis of vascular endothelial cells (VECs)." (PMID 34677370, 2021). "The treatment aimed at lowering the TNFα level is expected to delay the progression of mitochondrion dysfunction caused by telomere attrition due to hyperglycemia." (PMID 32454945, 2020). "To obtain more comprehensive details about the inflammatory processes caused by hyperglycemia, we examined the expression of TNF-α, IL-6, IL-8, and IL-1α." (PMID 33147748, 2020). "Older age, neutrophilia, thrombocytopenia, hyperglycemia and elevated LDH, serum creatinine, BUN, hs-cTnT, BNP, PCT, hsCRP, IL-6, IL-10, TNFα and poorly controlled hyperglycemia were also associated with death." (PMID 33382747, 2020). "During the pathogenesis of GDM, the level of pro-inflammatory cytokine TNF-α and IL-6 are elevated by hyperglycemia caused disorder in inflammation and oxidative stress." (PMID 31558153, 2019). "DM, hyperglycemia, and impaired glucose tolerance are associated with increased levels of IL-6, tumor necrosis factor (TNF)-α, and C-reactive protein (CRP)." (PMID 30298057, 2018). "Given that hyperglycemia induces chronic inflammation as a causative factor of cardiac remodeling, the expression levels of inflammatory markers, including p-P38, p38, TNF-α, IL-1β, CARD9, and BCL10, were examined by Western blot." (PMID 28272348, 2017). "Patients with liver disease have decreased energy intake due to anorexia caused by zinc deficiency, hyperglycemia and increased pro-inflammatory cytokine levels; tumor necrosis factor-alpha (TNF-α), interleukin (IL)-6 and leptin." (PMID 29035319, 2017). "One factor that is potentially involved in the regulation of insulin signaling is increased tumor necrosis factor alpha (TNFα) levels associated with hyperglycemia." (PMID 25874611, 2015). "We previously reported that the increase of SOCS3 and TNFα, in hyperglycemia, is associated with increased levels of IRS-1Ser307 phosphorylation and decreased phosphorylation of IRTyr1150/1151, leading to inhibition of normal insulin signaling." (PMID 25888955, 2015). "Overall, our results suggest that two essential components of T2D: hyperglycemia and the proinflammatory cytokine TNFα participates in reducing the risk of PCa in T2DM." (PMID 24058525, 2013). "HFFD-induced altered lipid profiles and hyperglycemia are closely associated with elevated pro-inflammatory cytokines, as we recorded increased concentrations of IL-1β, IL-6, and TNF-α." (PMID 23690866, 2013). "In patients with AbnGT, even under the identical postchallenge hyperglycemia levels, the dynamically postchallenge responses TNF-α and nitrotyrosine are significantly associated with the presence of CAD." (PMID 22397368, 2012).
Hyperglycemia (continued). "In addition, IR and hyperglycemia in the central nervous system (CNS) are associated with the TNF-α signaling pathway, which result in pain and hyperalgesia in DN." (PMID 38716357, 2024). "Hyperglycemia, as observed in T2D, is associated with inflammation characterized by elevated levels of proinflammatory cytokines, such as interleukin-6 (IL-6), tumor necrosis factor-alpha (TNF-α), and C-reactive protein (CRP) and these altogether increase the risk of CVD." (PMID 39683570, 2024). "First, stress-induced hyperglycemia is frequently associated with an upregulation of the immune-inflammatory response, leading to an increase in the release of pro-inflammatory cytokines such as interleukin-1, interleukin-6, and tumor necrosis factor-α." (PMID 38824608, 2024). "Increased inflammatory activity,as measured by elevated levels of IL-6 and TNF-, may be linked to hyperglycemia, as measured by HbA1c." (PMID 39132231, 2024). "In addition, berberine can inhibit the activation of NF-κB caused by hyperglycemia and the increase of pro-inflammatory factors and chemokines such as TNFα, IL1-β, IL8 and MCP1." (PMID 37780378, 2023). "Inhibition of these stimuli by metformin (reducing TNFα expression) and canagliflozin (reducing hyperglycemia) may diminish the pathogenic process of inflammation." (PMID 37240387, 2023). "Hyperglycemia can cause chronic inflammation, promote infiltration of inflammatory cells in renal tissues, and produce large amounts of proinflammatory factors, such as IL-1β, IL-6, and TNF-α." (PMID 36425593, 2022). "TNF-α increase may be associated with carbohydrate-related hyperglycemia, which has been shown to increase circulating cytokine concentrations by an oxidative mechanism." (PMID 35811952, 2022). "Hyperglycemia may also cause diabetic nephropathy through ROS activation, further accelerating the production of inflammatory cytokines such as IL-6 and TNF-α, leading to diabetic nephropathy." (PMID 35685736, 2022). "It has been hypothesized that elevated levels TNFα in presence of hyperglycemia might be important mechanisms that underlie the development of DKD9." (PMID 34045516, 2021). "However, inhibition or downregulation of PKC improves TNF-alpha- and hyperglycemia-caused oxidative stress and apoptosis in endothelial cells." (PMID 33658920, 2020). "Vascular endothelial cells are influenced by various factors (for example, endoplasmic reticulum stress, hyperglycemia, methylglyoxal, oxidized low density lipoprotein, ischemia-reperfusion, tumor necrosis factor-α (TNF-α), and lipopolysaccharide), and often cause apoptosis." (PMID 31723205, 2019). "On the other hand, a high sugar intake may induce hyperglycemia which is associated with spontaneous TNF-α secretion by peripheral monocytes due to downregulation of the CD33 membrane receptor that is responsible for inhibiting cytokine production." (PMID 30200631, 2018). "TNF-α can be released from MNCs and hyperglycemia causes an increase in ROS generation from MNCs." (PMID 28913143, 2017). "This excessive production of IL-6 and TNF-α may also be a result of oxidative stress and inflammatory changes caused by hyperglycemia." (PMID 27379252, 2016). "In mice with high-fat diet-induced hyperglycemia, hyperinsulinemia, and associated induction of TNF, a reduction of GLP-1-secretion was observed, which could be reversed by treatment with the TNF-neutralizing antibody etanercept." (PMID 27148273, 2016). "Maternal hyperglycemia associated with urinary incontinence creates an inflammatory environment, characterized by reduced melatonin and IL-10 and increased IL-1β, IL-8, and TNF-α in the plasma of mothers with gestational diabetes mellitus and incontinence-specific urinary tract issues." (PMID 41295285, 2025).
Hyperglycemia (continued). "This may be related to the continuous activation of cytokines such as interleukin-1 (IL-1), interleukin-6 (IL-6), and tumor necrosis factor-α (TNF-α) in diabetic patients, and the fact that hyperglycemia is associated with ROS production, leading to oxidative stress." (PMID 40783688, 2025). "Stress hyperglycemia and inflammation have some common pathogenic mechanisms since both are related with cytokines’ release, such as tumor necrosis factor-α (TNF-α), which might promote gluconeogenesis by stimulating glucagon production, as well as inhibit post-receptor insulin signaling." (PMID 39860413, 2025). "Hyperglycaemia is known to cause immune dysfunction, adversely affecting leukocyte function and leading to the increased production and secretion of cytokines, such as IL-6, IL-1β and TNF-α, leaving diabetic patients more susceptible to infections and related comorbidities." (PMID 37627482, 2023). "Hyperglycemia also stimulates the transcription nuclear factor (NF-κB), which in turn causes overexpression of specific gene sequences that control the regulation of numerous inflammatory cytokines, such as tumor necrosis factor-alpha (TNF-α), and cyclooxygenase-2 (COX-2)." (PMID 36278164, 2022). "It should be noted that hyperglycemia was also linked to an increased risk of infection in vitro and after surgical procedures, which is due to the excessive release of proinflammatory cytokines, such as tumor necrosis factor-α (TNF-α), interleukin-1 (IL-1) and interleukin-6 (IL-6)." (PMID 35273985, 2022). "It has been suggested that overexpression of miRNA 146a in diabetic patients may represent a protective defense mechanism by the body against inflammation by downregulating TNF-α and other target genes of the NF-κB pathway; thus, protect the body against the complications caused by hyperglycemia." (PMID 32756589, 2020). "In addition, short-term acute hyperglycemia caused by refined carbohydrate intake increased circulating levels of free radicals and proinflammatory cytokines such as interleukin (IL)-6, IL-18, and tumor necrosis factor-alpha." (PMID 31167515, 2019). "Thus, increased TNF release from MNC in response to hyperglycemia may be an underlying mechanism for IR in PCOS." (PMID 28913143, 2017). "Therefore, hyperglycemia-induced TNF-α release in patients with GDM may contribute to the underlying pathogenesis of GDM." (PMID 24348797, 2014). "Hyperglycemia stimulates the production of reactive oxygen species (ROS) and activates NF-κB, leading to the release of TNF-α and IL-6, perpetuating vascular dysfunction." (PMID 41993770, 2026). "Maternal hyperglycemia during pregnancy decreased IL-1β, increased TNF-α, and the receptor for advanced glycation end-products in the offspring hippocampus." (PMID 41590515, 2026). "Hyperglycemia increases the production of proinflammatory mediators, such as IL-6, IL-1β, and TNF-α, which play a crucial role in the development of chronic inflammation and thus impair immune system function." (PMID 41009326, 2025). "For instance, prolonged hyperglycemia induces macrophages to polarize towards the pro-inflammatory M1 phenotype, secreting numerous pro-inflammatory cytokines such as TNF-α and interleukin-1β (IL-1β), thereby exacerbating the inflammatory response." (PMID 40469434, 2025). "It has been proposed that hyperglycemia leads to the activation of TNF-alpha, which is critical in the development and progression of diabetic retinopathy." (PMID 40941666, 2025). "Hyperglycemia, especially under co‐culture conditions, significantly affected the secretion of IL‐6, TNF‐α, and adiponectin (p < 0.0001 for all), indicating its pervasiveness in adipokine regulation across these markers." (PMID 40746010, 2025). "Hyperglycemia and adipose tissue create a low-grade inflammatory state, increasing pro-inflammatory factors (e.g., TNF-α, IL-1β, IL-6) and ECM degradation." (PMID 41158135, 2025).
Hyperglycemia (continued). "Traumatic injury triggers substantial release of pro-inflammatory cytokines (IL-6, TNF-α, IL-1β) that induce stress hyperglycemia, which subsequently enhances neuronal excitability through glutamate-mediated mechanisms." (PMID 40303892, 2025). "Human aortic endothelial cells (HAEC) were treated with tumour necrosis factor-alpha (TNF-α, 20–50 ng/mL) and/or high glucose levels (30 mM) to replicate in vitro the states of inflammation and hyperglycaemia." (PMID 41326478, 2025). "Acute and persistent hyperglycemia increases intercellular adhesion molecule-1 levels and other inflammatory molecules (tumor necrosis factor-α, CRP), which would augment plugging of platelets and leukocytes in the capillaries." (PMID 40863381, 2025). "TNF-α production is induced by hyperglycemia through the activation of the NF-κB and MAPK pathway activation." (PMID 40149566, 2025). "Hyperglycemia stimulates the production of proinflammatory cytokines, including tumour necrosis factor‐alpha (TNF‐α), interleukins (IL‐1, IL‐6, IL‐12), adhesion molecules, and dendritic cells." (PMID 40931439, 2025). "Postprandial hyperglycemia, more than continuous hyperglycemia, triggers a transient increase in circulating proinflammatory cytokines, including tumor necrosis factor-α (TNF-α) and interleukin-6 (IL-6) through oxidative mechanism." (PMID 40671150, 2025). "We demonstrated that hyperglycemia increased the production of TNF and IL-6 by LPS-stimulated bone marrow-derived macrophages (BMDMs) and peritoneal macrophages." (PMID 41244562, 2025). "Long-term exposure to high-fat diets or hyperglycemia can impair endothelial cell function via inflammatory cytokines such as TNF-α, IL-1β, IL-6, and MCP-1." (PMID 40276785, 2025). "In cell-based and organ-on-a-chip models, preeclampsia, infection, or hyperglycemia can be mimicked by inducing hypoxia, adding pro-inflammatory cytokines (such as TNF-α or IL-6), or applying high-glucose culture conditions." (PMID 41221050, 2025). "Elevated pro-inflammatory mediators in obesity, including TNF-α, leptin, and resistin, disrupt cellular glucose uptake via suppression of insulin receptor signaling, culminating in hyperglycemia and diabetes." (PMID 41246338, 2025). "Hyperglycemia increases the production of glycation end products, reactive oxygen species, and proinflammatory cytokines (such as Tumor Necrosis Factor Alpha (TNF-α) and interleukin-6 (IL-6)) in plasma." (PMID 41578817, 2025). "TNF-α further exacerbates chronic hyperglycemia by stimulating the release of additional cytokines and chemokines that activate NF-κB." (PMID 40507069, 2025). "Circulating levels of proinflammatory cytokines such as interleukin (IL)−6, IL-18, and tumor necrosing factor-α (TNF-α) are revealed to be elevated by acute hyperglycemia-induced oxidative stress." (PMID 39812937, 2025). "The inflammatory pathway is also triggered by hyperglycemia-induced oxidative imbalance, leading to elevated levels of pro-inflammatory cytokines such as interleukin-1β (IL-1β), tumor necrosis factor-alpha (TNF-α), and vascular adhesion molecules (VCAMs)." (PMID 40772141, 2025). "The activation and stimulation of macrophages and endothelial cells following oxidative stress induced by hyperglycemia lead to the activation of IκB kinase (IKKβ) and the transcription factor NF-κB, resulting in an increased secretion of TNF-α." (PMID 41287754, 2025). "During hyperglycemia, the overproduction of reactive oxygen species (ROS) triggers the release of pro-inflammatory cytokines such as IL-6, IL-1β, TNF-alpha, and IFN-γ." (PMID 39940428, 2025). "Consistent with previous reports, systemic improvements in hyperglycemia, insulin sensitivity, and reductions in peripheral inflammatory cytokines (e.g., TNF-α, IL-6) were observed in MSC-treated DM models." (PMID 40244194, 2025).